METTL1 (methyltransferase 1, tRNA methylguanosine)
Diseases named in the same sentence as METTL1 in open-access papers (continued):
Sharing a sentence is not in itself a finding about the gene and the disease.
tumor (continued). "Collectively, these findings suggest that METTL1 exerts multifaceted and multilayered effects on tumorigenesis and immune regulation, providing a foundation for understanding the tumor immune microenvironment and developing METTL1-based immunotherapeutic strategies." (PMID 41562049, 2025). "Previous work has identified elevated tumor aneuploidy as a marker of low overall survival and can be used as a biomarker for clinical outcomes of immunotherapy, and we found that the copy number value of METTL1 altered samples had higher aneuploidy score." (PMID 40443650, 2025). "Overall, these studies confirm that while METTL1 expression may vary across different tumor types, it consistently regulates tumor growth." (PMID 39870616, 2025). "As a well-known methyltransferase, METTL1 is overexpressed in various tumor tissues and cell lines." (PMID 39870616, 2025). "Furthermore, disrupting METTL1/TGF‐β/PMN‐MDSC axis significantly mitigates tumour progression by decreasing PMN‐MDSC accumulation and restoring the CD8+ T‐cell population after RFA." (PMID 39979979, 2025). "Other scholars have demonstrated that METTL1 can modify the immune microenvironment by regulating the infiltration of various immune cell types, including T cells and macrophages, thereby affecting anti-tumor immune responses." (PMID 40809384, 2025). "METTL1 expression was significantly elevated in tumor tissues relative to normal skin tissues." (PMID 39870616, 2025). "METTL1 is often aberrantly expressed and catalyzes m7G modification in tRNAs or miRNAs, which ultimately affects the expression of target genes and regulates tumor-related biological functions." (PMID 40443650, 2025). "Additionally, METTL1-mediated m7G modifications on mRNAs can increase transcript stability, further contributing to the accumulation of key proteins involved in tumor progression." (PMID 41562049, 2025). "However, further investigation is needed to understand the differential expression of METTL1 in cSCC and the role of m7G modification in the development of this tumor type." (PMID 39870616, 2025). "Recent studies suggest that blocking the axis of METTL1-TGF-β2-PMN-MDSC may be a therapeutic strategy to restore anti-tumor immunity and reduce HCC recurrence after radio frequency ablation (RFA) therapy." (PMID 39850560, 2024). "On the contrary, smaller tumor was observed in mice injected with METTL1‐knockdown LUAD cells." (PMID 38967523, 2024). "Interestingly, our study revealed, for the first time, that METTL1 acted as a tumor suppressor in BC, which diverges from its role in most of the tumor types." (PMID 38822363, 2024). "Larger subcutaneous tumor was observed in mice injected with METTL1‐overexpressed LUAD cells." (PMID 38967523, 2024). "With its dual role as an oncogene and a tumor suppressor gene, downregulation of tRNA m7G methylation by METTL1 has been shown to promote the proliferation and angiogenesis of human-induced pluripotent stem cells in nude mice, leading to the formation of teratomas." (PMID 39155349, 2024). "For example in HCC, METTL1 expression promotes tumor resistance to both radiotherapy and the tyrosine kinase inhibitor levatinib, enhancing the translation of the DNA double-strand break (DSB) repair enzyme DNA ligase IV or components of the EGFR pathway, respectively." (PMID 38476632, 2024). "Thus, the combination of METTL1 and abemaciclib inhibits tumor growth through a two-pronged approach." (PMID 38822363, 2024). "Only recent studies have suggested that targeting autophagy could be a promising approach for treating tumours with high METTL1 expression." (PMID 37660182, 2023). "METTL1 mediates m7G methylation in miRNAs and promotes tumor cell migration." (PMID 36935487, 2023). "Recent studies have shown that the METTL1 / WDR4 complex can promote tumor progression." (PMID 37528384, 2023). "In addition, METTL1/WDR4 had a better ability to distinguish tumor from non-tumor (AUC > 0.6) based on ROC curves." (PMID 37528384, 2023).
tumor (continued). "Immunohistochemical analysis revealed a significant increase in intratumoural infiltration of M1-like macrophages (iNOS+) at the expense of M2-like macrophages (Arg1/CD68+), and an increase in CD8 + T cells in Mettl1 +/- and Mettl1flox/flox tumours compared to Mettl1+/+ tumours." (PMID 37516825, 2023). "Consequently, the inhibition of METTL1, alone or in combination with chemotherapeutic options, leads to a substantial reduction in tumour mass, resulting in tumours that resemble the architecture of healthy tissue." (PMID 37660182, 2023). "Thus, future functional validations showing how METTL1-expressing tumour cells interact with their neighbouring immune cells will lead to a better understanding of PCa progression." (PMID 37516825, 2023). "Thus, our data indicated that METTL1 downregulation can effectively decrease tumour growth, strongly supporting that METTL1 is crucial in the regulation of PCa progression." (PMID 37516825, 2023). "METTL1 downregulation also diminished cell division, induced cell cycle arrest, increased apoptosis, impaired spheroid formation capacity, and drastically reduced the growth and proliferation of tumour xenografts." (PMID 37516825, 2023). "To assess whether METTL1 inhibition could reduce the tumour growth and affect the intratumoural immune composition in vivo, we deleted Mettl1 in Pten-KO mice." (PMID 37516825, 2023). "M7G methylation mediated by METTL1 promotes tumor proliferation in the early stages of LUAD." (PMID 36635678, 2023). "This evidence suggests that both METTL1 expression and m7G deposition levels may serve as potential tumour biomarkers." (PMID 37516825, 2023). "Reduced modification and therefore reduced translation of tumor-related mRNAs result from the depletion of the m7G modification enzymes METTL1/WDR4, which affects the potential of tumor cell division, colony formation ability, tumor cell migration and invasion ability and tumorigenic potential." (PMID 38201505, 2023). "The insights gained from this research open up new possibilities for targeted therapies that modulate METTL1 activity, which may enhance the anti-tumour immune response and improve patient outcomes in PCa." (PMID 37516825, 2023). "Upregulation of the METTL1/WDR4 complex promotes tumor development and metastasis." (PMID 37710294, 2023). "Given that METTL1 KO cells synthesise fewer proteins, we hypothesised that METTL1 inhibition could reduce cell and tumour growth." (PMID 37516825, 2023). "Some studies suggest METTL1 is a potential tumor suppressor." (PMID 35986847, 2022). "METTL1 actively participates in multiple tumor progression-related processes in CC by regulating the expression levels of various miRNAs, which may provide insight into novel therapeutic targets for CC." (PMID 35590385, 2022). "Our TMB and MSI analyses for METTL1 and WDR4 reflected the mutation frequency and proportion at the molecular level in different tumors and showed the correlation between mutation load and tumor progression." (PMID 36226166, 2022). "In addition, Immunohistochemistry (IHC) staining revealed the increased METTL1 expression in ESCC tumors than that in peri-tumor tissues." (PMID 35304469, 2022). "Consequently, the tumor suppressor role of ATF3 made a further statement that ATF3 was a target gene regulated by METTL1-modified miR-760." (PMID 36396627, 2022). "Moreover, a positive correlation between the expression of METTL1 and both advanced clinical stage and high tumor grade has been observed in bladder cancer." (PMID 36482181, 2022). "In conclusion, METTL1 was indispensable for tumor proliferation and metastasis in vivo." (PMID 36396627, 2022). "High METTL1 expression was related to tumor progression-relevant pathways." (PMID 35432338, 2022). "In vivo, tumor growth and metastasis were significantly suppressed upon METTL1 deletion." (PMID 36396627, 2022). "Moreover, METTL1 exhibited a distinct correlation with tumor immune microenvironment infiltration and stemness indices." (PMID 35432338, 2022).
tumor (continued). "METTL1-knockout mice exhibit lower tumor burden and longer survival than wild-type controls." (PMID 35590385, 2022). "Considering the mRNA regulating effect of miRNA and miRNA regulating effect of METTL1, we screened genes negatively correlated with METTL1 and confirmed tumor suppressor ATF3 was the downstream target of METTL1-modified miR-760, which was confirmed by dual-luciferase reporter assay." (PMID 36396627, 2022). "Notably, METTL1-knockout mice exhibit reduced hepatocarcinogenesis as compared with control mice, showing slower tumor formation and reduced tumor burden." (PMID 35590385, 2022). "The expression of METTL1 obviously increased in tumor tissue compared to normal tissue." (PMID 33589575, 2021). "IHC analysis confirmed that METTL1‐depleted tumours had reduced METTL1 protein expression." (PMID 34936728, 2021). "Here, we found that METTL1‐mediated m7G tRNA modification and m7G codons regulate mRNA translation through mRNA codon frequency‐dependent manner, which demonstrates a novel mechanism of selective translation leading to malignant tumour behaviour." (PMID 34898034, 2021). "Furthermore, data from Oncomine databases showed that METTL1 expression varied significantly across tumor tissues." (PMID 34838021, 2021). "Furthermore, IHC staining showed that tumours in the Mettl1‐cKO mice had lower percentage of Ki67‐positive cells and decreased intensity of HCC marker AFP." (PMID 34898034, 2021). "In addition, H&E staining showed that there were significantly decreased tumour lesions in Mettl1‐cKO mice." (PMID 34898034, 2021). "The expression of METTL1 in BC tumour tissues was remarkably higher than in normal tissues." (PMID 34936728, 2021). "The increased vascularization might explain the fact that the downregulation of METTL1 in hiPSCs enhanced in vivo tumor formation and progression." (PMID 32698871, 2020). "Furthermore, METTL1 can directly influence tumor responsiveness to immunotherapy by regulating key immune checkpoints (e.g., PD-L1, CTLA-4), immune regulatory molecules (modulating interferon signaling), and proinflammatory immune cell activity, indicating its potential as a therapeutic target." (PMID 41562049, 2025). "Furthermore, a positive correlation between ATF4 and METTL1 was observed in cSCC tumor tissues." (PMID 39870616, 2025). "However, further research is needed to determine whether METTL1 is involved in the angiogenesis of other malignancies and affects the malignant process of tumours." (PMID 39979979, 2025). "We hypothesized that METTL1 might be related to immune cell infiltration and the response to immunotherapy since T cell migration and the inflammatory response are crucial for anti-tumor immunity." (PMID 40443650, 2025). "Additionally, METTL1 may influence the tumor immune microenvironment by modulating antigen presentation or affecting immune effector cell function to facilitate immune evasion." (PMID 41562049, 2025). "METTL1 also contributes to metabolic homeostasis by selectively promoting the translation of enzymes and transporters involved in glucose metabolism, lipid biosynthesis, and amino acid balance, providing energy and biosynthetic precursors for rapidly proliferating tumor cells." (PMID 41562049, 2025). "By modulating tRNA stability, translational efficiency, and protein synthesis, METTL1 not only promotes tumor cell proliferation, migration, and metabolic reprogramming but may also contribute to immune evasion through its effects on antigen processing and immune cell function." (PMID 41562049, 2025). "In addition, GO analysis revealed that METTL1 knockdown-mediated downregulation of genes and proteins was required for generating the biological processes of cell adhesion and population proliferation, which led to tumor proliferation and metastasis." (PMID 40360483, 2025). "Additionally, we found that the METTL1 gene was overexpressed in tumor tissues of GSE84437." (PMID 38693422, 2024).
tumor (continued). "Next, we examined whether METTL1 expression levels helped to define patients with PTEN-loss-associated decreased survival, which is of clinical relevance, and distinguish indolent from aggressive disease in patients with clinically localised tumours." (PMID 37516825, 2023). "Additionally, deconvolution analysis of PCa expression datasets using CIBERSORT or TIMER showed a significant inverse correlation between intratumoural M1-like macrophage composition and METTL1, indicating a more cytotoxic immune tumour component in METTL1-low tumours." (PMID 37516825, 2023). "METTL1 may also promote tumor progression in some other conditions." (PMID 37612540, 2023). "In addition, Mettl1‐KI mice had increased tumour densities than the control mice." (PMID 34898034, 2021). "Overall, METTL1 promotes HNSC malignancy by regulating global mRNA translation, including PI3K/AKT/mTOR pathway transcripts, while reshaping the tumor immune microenvironment, highlighting its potential as a therapeutic target." (PMID 41562049, 2025). "METTL1 promotes PMN–MDSC accumulation via m7G, inhibiting tumor‐specific T cell activity and reducing ICC tumor cell sensitivity to PD‐1 therapy." (PMID 39802639, 2025). "METTL1 plays a role in promoting CDK11 and ATF5 mRNA stability in an m7G manner, impacting tumor progression." (PMID 40809690, 2025). "METTL1 enhanced BRCA1 expression via m7G modification, boosting cell proliferation and tumor growth." (PMID 41430564, 2025). "METTL1 overexpression stimulates the proliferation, migration and invasion of ACC cells, whereas METTL1 silencing significantly retards tumour growth in mouse xenograft model." (PMID 39979979, 2025). "Blocking the METTL1–TGF-β2–PMN-MDSC axis (e.g., via anti-Ly6G antibody, hepatocyte-specific METTL1 or Tgfb2 knockdown, or inhibition of TGF-β signaling) markedly attenuates iRFA-induced tumor progression and restores CD8+ T cell levels." (PMID 41562049, 2025). "Collectively, these results indicate that METTL1 plays a pro‐oncogenic role in ACC progression and profoundly affects the tumour immunity of ACC." (PMID 39979979, 2025). "Clinically, ACC samples with high METTL1 expression exhibit reduced CD8+ T cell infiltration and increased macrophage infiltration; METTL1 knockdown significantly inhibits xenograft tumor growth in mice." (PMID 41562049, 2025). "For instance, METTL1 stabilizes Ribosomal RNA Processing 9, U3 Small Nucleolar RNA Binding Protein (RRP9) mRNA via m7G modification, thereby promoting tumor cell proliferation and metastasis in CRC." (PMID 40809384, 2025). "METTL1 has been shown to enhance VEGFA mRNA translation in a manner dependent on m7G methylation, thereby facilitating tumor progression." (PMID 40809690, 2025). "The functional investigation of METTL1 and BRCA1 revealed that METTL1 mediated the upregulation of BRCA1 through m7G modification, thereby promoting cell proliferation and tumor growth in HGSOC." (PMID 41430564, 2025). "In HCC and ICC, knockout of METTL1/WDR4 lowers global tRNA m7G levels, suppresses codon‐biased translation of cell‐cycle and survival mRNAs, and attenuates tumour growth in vitro and vivo." (PMID 41208200, 2025). "A few METTLs, such as METTL1, METTL14 and METTL16, also showed oncogenic effects, to systematically delineate the distinct roles of METTL family members across tumor types, we generated a comprehensive schematic." (PMID 41194259, 2025). "Mechanistically, METTL1 selectively enhances the translation of human CXCL8 and murine Cxcl5, facilitating PMN-MDSC recruitment and tumor growth." (PMID 41562049, 2025). "Mechanistic studies reveal that METTL1 stabilizes ICAM-1 mRNA via m7G modification, promoting tumor progression." (PMID 41562049, 2025). "In OSCC, METTL1/WDR4‐driven tRNA m7G modification enhances the selective translation of growth and EMT‐related transcripts, driving tumour progression." (PMID 41208200, 2025).
tumor (continued). "Recent studies have demonstrated that METTL1-mediated m7G modification of PKM mRNA enhances PKM2 protein expression, thereby promoting tumor progression and glycolytic activity." (PMID 41562049, 2025). "Recent studies indicate that METTL1-mediated tRNA m7G modification plays a crucial role in regulating HNSC tumor growth, signaling pathway activation, and the tumor immune microenvironment." (PMID 41562049, 2025). "Mechanistically, the context determinants that toggle METTL1/WDR4 outputs between oncogenic, codon‐biased selective translation and miRNA‐centred tumour suppression are incompletely resolved at the patient level." (PMID 41208200, 2025). "To investigate the clinical significance of METTL1-mediated codon-specific translation of TNF-α in PTC patients, we utilized PTC tumor tissues to validate the translational and clinical relevance of METTL1, WDR4, and TNF-α interactions." (PMID 40360483, 2025). "This modification exerts selective control over the selective translation of oncogenic mRNAs governed by a codon frequency–dependent mechanism, primarily orchestrated by the METTL1/WDR4 complex, thereby influencing tumour growth and malignancy." (PMID 41208200, 2025). "Knockdown of METTL1 markedly reduces PTC cell proliferation and migration, indicating that its tumor-promoting effects rely on the presence of functional m7G tRNA modification." (PMID 41562049, 2025). "RNA m7G modification plays a pivotal role in tumor development, and METTL1 has been shown to mediate m7G modification of PKM2 mRNA, enhancing its translation and upregulating PKM2 protein levels, thereby promoting tumor progression and glycolytic activity." (PMID 41562049, 2025). "As a result, this study validates the potential therapeutic role of METTL1‐mediated tRNA m7G modification in AML cell translation control and tumour biology." (PMID 39979979, 2025). "This study highlights the novel finding that 5-formamidoimidazole-4-carboxamide ribotide suppresses BRCA1 expression by inhibiting METTL1-mediated m7G modification, ultimately leading to the inhibition of HGSOC cell proliferation and tumor growth." (PMID 41430564, 2025). "The expression of METTL1 and WDR4 in PTC tumor tissues was significantly greater than that in normal tissues." (PMID 40360483, 2025). "In future studies, we plan to investigate the synergistic effect of LARP1 with other known prognostic molecules (such as EIF3D, EIF1, METTL1) in HNSCC, particularly their potential interactions in tumor cell growth, metastasis, and immune evasion." (PMID 40018039, 2025). "Orthotopic transplantation models showed that both METTL1 knockout and WDR4 knockdown significantly hindered tumour growth and lymph node metastasis." (PMID 41208200, 2025). "Among them, m7G acts through METTL1/WDR4 and eIF4E to shape translation and RNA processing across coding and non‐coding transcripts, yielding oncogenic or tumour‐suppressive outputs in a context‐dependent manner." (PMID 41208200, 2025). "Initially, the expression levels of METTL1 and ATF4 in the tumor tissues were examined, revealing a significant enhancement in ATF4 expression in tumors originating from cells harboring the overexpression of ATF4." (PMID 39870616, 2025). "In oral squamous cell carcinoma (OSCC), evidence indicates that METTL1/WDR4‐driven tRNA m7G enhances selective translation of growth and EMT programmes, thereby promoting tumour progression." (PMID 41208200, 2025). "Upregulation of the METTL1/WDR4 complex in NPC induces epithelial–mesenchymal transition (EMT) by activating the Wnt/β-catenin signaling pathway, thereby enhancing tumor metastasis." (PMID 41446042, 2025).